CS (citrate synthase)
Diseases named in the same sentence as CS in open-access papers (continued):
Sharing a sentence is not in itself a finding about the gene and the disease.
ovarian carcinoma (11 papers, 2014 to 2025). A malignant neoplasm originating from the surface ovarian epithelium. "Increased CS activity and expression have been reported in human pancreatic cancer, lymphoma, and ovarian cancer." (PMID 41515967, 2025). "In ovarian cancer, the expression of CS is upregulated, promoting cell proliferation, invasion, and migration." (PMID 40557149, 2025). "Studies in SKOV3 and A2780 cells (ovarian cancer cell lines) indicated that knockdown of the CS gene inhibited cell proliferation, migration, and invasion, and enhanced chemotherapy sensitivity." (PMID 38693171, 2024). "In different types of cancer, and especially in ovarian cancer, the genes encoding for the enzymes aconitase, isocitrate dehydrogenase (IDH), succinate dehydrogenase (SDH) and citrate synthase (CS) were deregulated." (PMID 37110218, 2023). "Knocking down CS using RNAi mechanism resulted in reduced proliferation, migration, and invasion in in vitro studies using ovarian cancer cell lines." (PMID 37110218, 2023). "Here, we provided the first demonstration that inactivation of CS result in defective cell proliferation, cellular invasion, migration, and increased chemosensitivity in ovarian cancer cells." (PMID 25545012, 2014). "Given that CS was overexpressed in ovarian cancer, we further investigate the effect of CS on drug resistance of ovarian cancer cells." (PMID 25545012, 2014). "In this study, we found higher CS expression in malignant ovarian tumors and ovarian cancer cell lines compared to benign ovarian tumors and normal human ovarian surface epithelium, respectively." (PMID 25545012, 2014). "Results showed mRNA expression of CS in ovarian carcinoma tissues was 1.843 times of ovarian benign tumors (P = 0.0064), the protein level was also upregulated in human ovarian carcinoma compared with the benign tumors." (PMID 25545012, 2014). "Citrate synthase (CS) was overexpressed in malignant ovarian tumors compared to benign tumors." (PMID 40868085, 2025). "Citrate Synthase knockdown has been described to be synergetic with cisplatin in ovarian cancer." (PMID 38425123, 2024). "CS was overexpressed in malignant ovarian tumors compared to benign tumors." (PMID 37110218, 2023). "CS is overexpressed in ovarian cancers and cell lines compared to controls." (PMID 35498135, 2022). "CS upregulation has been observed in other ovarian cancer studies." (PMID 34078919, 2021). "This deregulation could be related to a possible resistance mechanism as was previously reported in ovarian carcinoma where, after chemotherapy, an increase of CS expression levels was related to protection from apoptosis." (PMID 31370342, 2019). "In order to find out whether CS was abnormally expressed in human ovarian tissues and cells, we compared mRNA and protein expression of CS in human ovarian carcinoma tissues, ovarian benign tumors and normal HOSE." (PMID 25545012, 2014). "CS knockdown by RNAi could result in the reduction of cell proliferation, and inhibition of invasion and migration of ovarian cancer cells in vitro." (PMID 25545012, 2014). "The activity of CS in ovarian cancer has been studied previously." (PMID 25545012, 2014). "Taken together, these results suggested that CS might represent a potential therapeutic target for ovarian carcinoma." (PMID 25545012, 2014). "In order to study whether the up-regulated expression of CS was correlated with malignant phenotype of ovarian cancer, siRNA was applied on human ovarian adenocarcinoma cell lines." (PMID 25545012, 2014). "In current study, based on observation that high expression of CS in malignant ovarian tumors and ovarian cancer cell lines, we hypothesized that CS might contribute to the ovarian cancer phenotype as well as drug resistance and thus represent a therapeutic target." (PMID 25545012, 2014).
ovarian carcinoma (continued). "Taken together, these findings suggested that CS play an important role in regulation of ovarian cancer cell proliferation, invasion, migration, and chemoresistance and indicated that inhibition of CS could be a potential therapeutic strategy for treatment of ovarian cancer." (PMID 25545012, 2014). "The results suggested CS silencing could promote ovarian cancer cell apoptosis." (PMID 25545012, 2014). "Yet in ovarian cancer cell lines SKOV3 and A2780, CS RNAi reduced cell proliferation, inhibited cell migration, and modestly increased ATP production." (PMID 41515967, 2025). "We evaluated the consequences of transient CS inactivation by silencing the CS gene in SKOV3 and A2780 ovarian cancer cell lines." (PMID 25545012, 2014).
Sepsis (11 papers, 2013 to 2025). Sepsis is defined as life-threatening organ dysfunction caused by a dysregulated host response to infection. "Like CS activity, mtDNA:nDNA ratio was lower in febrile illness than controls (p = 0.05) and was also lower compared to those with sepsis (p < 0.01)." (PMID 39095577, 2025). "Another group of proteins that plays an important role in sepsis is complement (CS), the main component of the innate immune system against pathogens." (PMID 36459524, 2022). "In monocytes, maximum levels of citrate synthase activity in sepsis were significantly lower when compared to controls (p = 0.021)." (PMID 28591158, 2017). "Some authors have noted that platelet citrate synthase activity relates to other markers of mitochondrial content, such as mitochondrial DNA, and remains normal during human sepsis." (PMID 25757508, 2015). "In relation to mtDNA and CS activity, ATP-generating respiration tended to be lower in the sepsis patients as compared with controls." (PMID 23883738, 2013). "The already described pro-inflammatory environment due to MD might be related to these changes in mitochondrial density, since decreases in brain CS activity have been reported in animal models of sepsis." (PMID 39765678, 2024). "Importantly, we identified six critical genes, including CS, CYP1B1, FLVCR1, IFIT2, MAPK14, and PID1, which showed favorable diagnostic value in screening sepsis samples from normal samples." (PMID 37398680, 2023). "Finally, we collected 15 sepsis samples and 15 normal samples and performed RT-PCR to examine the expression of CS, CYP1B1, FLVCR1, IFIT2, MAPK14, and PID1 in our cohort, which further confirmed our previous findings." (PMID 37398680, 2023). "Using bioinformatics techniques, we identified PID1, CS, CYP1B1, FLVCR1, IFIT2, and MAPK14 as six MRGs that are essential in the course of sepsis." (PMID 37398680, 2023). "We found that the expression of MAPK14 and CYP1B1 was distinctly increased in sepsis samples compared with normal samples, while the expression of PID1, CS, FLVCR1, and IFIT2 was distinctly decreased in sepsis samples compared with normal samples." (PMID 37398680, 2023). "Citrate synthase activity was not affected by sepsis, reaching 64.2 ± 12 and 62.1 ± 11 IU/g in control and septic samples, respectively." (PMID 29946267, 2018). "In fact, other spectrophotometric works did show inhibition of complex I and (possibly) complex IV, with or without a parallel decrease of citrate synthase activity, in vastus lateralis muscle of patients with sepsis, especially if severe or prolonged." (PMID 24787741, 2014). "One previous study reported lower platelet complex IV and higher platelet citrate synthase activities in patients with severe sepsis who finally died compared to those who did not." (PMID 24787741, 2014). "Reduced skeletal muscle mitochondrial enzyme activity has been observed in patients with sepsis and multiple organ failure if expressed per wet muscle weight, but not if normalized to citrate synthase activity, a marker of mitochondrial content." (PMID 23363690, 2013). "Thus, in a previous study of 96 patients with severe sepsis, we found that 6-month survivors had higher platelet COX activity normalized by citrate synthase (CS) activity at the time of diagnosis than non-survivors." (PMID 24981786, 2014).
heart failure (9 papers, 2012 to 2022). Inability of the heart to pump blood at an adequate rate to meet tissue metabolic requirements. "Heart failure decreases the capacity for oxidative metabolism in myocardium, as reflected in a decrease in the activities of citrate synthase, aconitase and medium-chain acyl-CoA dehydrogenase (MCAD)." (PMID 29421236, 2018). "One challenge in accomplishing this increase is that activity of the enzymes aconitase and citrate synthase are decreased in heart failure." (PMID 23560088, 2013). "Finally, the effectiveness of exercise training was demonstrated by increased exercise capacity, peak VO2, citrate synthase activity and resting bradycardia in the trained heart failure animals." (PMID 23300764, 2012). "Furthermore, the activity of citrate synthase, the initial enzyme in the citric acid cycle, may be reduced in heart failure owing to the inability of the mitochondria to transport electrons and perform oxidative phosphorylation, thereby compromising energy production." (PMID 35204132, 2022). "CS and HADH activity significantly declined only at the 4-week time point in hearts of both genotypes at a time when overt heart failure was present." (PMID 36125265, 2022). "We also measured the activities of these enzymes in both subpopulations separately and we found that citrate synthase and MCAD were decreased by heart failure-induced by pressure overload in IFM and SSM whereas aconitase as not altered by hear failure in the isolated mitochondria." (PMID 29421236, 2018). "PDH activity was significantly increased in the heart failure group when normalized to citrate synthase activity (4.49 ± 0.49 mU/U citrate synthase), representing a 63% increase compared to the nonfailing tissues (2.75 ± 0.51 mU PDH/U citrate synthase, p = 0.023)." (PMID 30881593, 2019).
type 2 diabetes (9 papers, 2011 to 2022). "An inborn defect in the CS enzyme is hypothesized to cause low rates of fatty acid oxidation in the cell cultures generated from muscle biopsies of patients with type 2 diabetes." (PMID 29095821, 2017). "Glycolysis (triosephosphate isomerase 1 and phosphoglycerate kinase 1), citrate cycle (citrate synthase and malate dehydrogenase 2) and type II diabetes mellitus (pyruvate kinase) were among the other pathways identified for these proteins." (PMID 30419808, 2018). "Citrate synthase is a key mitochondrial enzyme that is commonly used as a quantitative marker for the content of intact mitochondria and its activity is reduced in muscles of type 2 diabetic patients." (PMID 35328751, 2022). "These investigators found that muscle mitochondria of type 2 diabetic patients had a significantly reduced activity of NADH oxidase and electron transport chain (ETC) activity but no deficiency of citrate synthase or β-hydroxyacyl-CoA dehydrogenase activities." (PMID 21589859, 2011).
colon carcinoma (8 papers, 2016 to 2025). "SIRT5 can desuccinylate the key TCA metabolic enzyme citrate synthase(CS) at K393 and K395, enhancing its activity and promoting colon cancer cell proliferation and migration." (PMID 39781339, 2025). "BBR inhibited the growth of human colon cancer cell lines Caco-2 and Lovo by reducing citrate synthase activity." (PMID 36937842, 2023). "This was concomitant with a decrease of mitochondrial mass, characterized by reductions in citrate synthase expression in the colon cancer cells." (PMID 27206796, 2016). "Citrate synthase (CS), the first rate-limiting enzyme of the TCA cycle, upregulates its activity after desuccinylation by SIRT5 at K393 and K395, promoting colon cancer cell proliferation and migration." (PMID 39979670, 2025).
ischemia (8 papers, 2011 to 2024). A hypoperfusion of the BLOOD through an organ or tissue caused by a PATHOLOGIC CONSTRICTION or obstruction of its BLOOD VESSELS, or an absence of BLOOD CIRCULATION. "In the samples from all time points, citrate synthase activity was similar to the sham controls, indicating preservation of mitochondrial mass, for 24 hours post-ischemia." (PMID 29643256, 2018). "Both ischemia injured groups showed reduced citrate synthase-normalized cytochrome c activity, as well as reduced rate of ATP production, but the lowest level were in any case assessed in the L-T3S rats." (PMID 26561807, 2015). "It is possible that ischemia/reperfusion-induced phosphorylation of ATP synthase (alpha and/or beta subunit) and citrate synthase via δPKC activation may be responsible for lower activities of these two enzymes." (PMID 21789211, 2011). "Surprisingly, activity of HADH and citrate synthase were not affected by ischemia, suggesting that the reduced ATP content was due to dysfunction of mitochondrial complexes rather than loss of mitochondria." (PMID 25889299, 2015). "In our current study, we observed that the citrate synthase activity was not significantly changed by 2 h of ischemia but was increased after reperfusion following 2 h of MCAO." (PMID 24667167, 2014).
melanoma (7 papers, 2013 to 2025). A malignant, usually aggressive tumor composed of atypical, neoplastic melanocytes. "Overexpression of CS in CREB overexpressing A375 melanoma cells (CREBTG/CS) suppressed the melanoma growth in the transplant mouse model." (PMID 41258756, 2025). "The melanoma-bearing groups also showed increased citrate synthase activity with exercise, but this increase was only significant in the mice maintained on a high-fat diet." (PMID 31528182, 2019). "To reiterate, evaluation of the activity of OXPHOS complexes showed higher levels in BRAF-mutated and BRAF/NRAS wild-type melanoma cell lines compared to HDFs, most likely due to a higher mitochondrial mass as indicated by VDAC1 immunostaining and activity of citrate synthase." (PMID 33007949, 2020). "Furthermore, a reduction in β-catenin expression could significantly increase cellular metabolism in the PTENWT melanoma cells as demonstrated by increased CS activity and lactate secretion, compared with control siRNA-treated cells." (PMID 28092677, 2017). "In fact, both melanoma cell lines exhibited OCR values higher than melanocytes; and in parallel experiments we also observed higher citrate synthase activity in both cancer cell lines compared to melanocytes (data not shown)." (PMID 23603840, 2013). "By contrast, virtually no double staining of pCREB and either citrate synthase (CS) or aconitase (ACO2), key enzymes in the TCA cycle, was detected in sections from old patients with human primary melanomas." (PMID 41258756, 2025).
Alzheimer disease (6 papers, 2021 to 2025). A progressive, neurodegenerative disease characterized by loss of function and death of nerve cells in several areas of the brain leading to loss of cognitive function such as memory and language. "Consequently, these two genes were excluded, leaving six critical genes with diagnostic significance for Alzheimer’s disease (AD): ACO2, CS, MRPS27, SDHA, SLC25A20, and SYNJ2BP." (PMID 39757625, 2025). "OGT is positively correlated to citrate synthase protein levels, lactate dehydrogenase (LDH) activity and postsynaptic density protein 95 (PSD95), which is an important postsynaptic scaffolding protein and decreased levels are associated with Alzheimer disease pathology." (PMID 35248135, 2022).
cervical carcinoma (6 papers, 2014 to 2025). A carcinoma arising from either the exocervical squamous epithelium or the endocervical glandular epithelium. "In cervical cancer cells, inhibition of citrate synthase expression induces epithelial-mesenchymal transition (EMT), thereby enhancing the malignant characteristics of tumor cells." (PMID 40557149, 2025). "For example, RNAi-mediated CS knockdown in human cervical carcinoma cells impaired Δψm, accelerated cytosolic glycolysis, and reduced ATP production." (PMID 30678035, 2019). "Evidence for a role of citrate synthase (CS) in cancer is sparse and controversial: CS was found to be increased in pancreatic ductal carcinoma and renal oncocytoma but downregulated in various cervical cancer cell lines." (PMID 25057353, 2014). "Indeed, CS knockdown also promotes reliance on anaerobic glycolysis and stimulates proliferation of human cervical carcinoma cells." (PMID 29095821, 2017). "Also reduced CS activity may favor metastasis, since its knockdown can induce an EMT phenotype and enhance metastasis in cervical carcinoma cells, although the contrary can occur in other cancers." (PMID 34674701, 2021).
lung carcinoma (6 papers, 2014 to 2024). "To confirm specificity of CS expression in this context we verified the effect of CHKA inhibition in A549 human lung cancer cells and isogenic cells with depleted mtDNA (A549 Rho)." (PMID 27206796, 2016). "Knockdown of ATP citrate lyase was shown to reverse EMT in lung cancer cells, while knockdown of citrate synthase was found to induce EMT." (PMID 25502225, 2014). "Here, we demonstrated that, in a urethane-induced lung cancer mouse model, the Retro-Tf-D-LP4 peptide reached the lung and attenuated tumor growth, and also decreased the expression of metabolic-related enzymes such as VDAC1 and the TCA cycle enzyme citrate synthase." (PMID 39272828, 2024).
COVID-19 (5 papers, 2021 to 2024). A disease caused by infection with severe acute respiratory syndrome coronavirus 2. "Citrate synthase activity was similar among control, LPS-, and LPS+COVID-19 spike S1 + S2 subunit-incubated HPMEC." (PMID 36438904, 2022). "Furthermore, the upregulation of CS genes C1S and C1R and the downregulation of the genes regulating CS (C1q) during COVID-19 further corroborate the role of CS hyperactivation in immunopathology." (PMID 33757410, 2021). "Moreover, in LPS-incubated HPMEC and with the presence of recombinant COVID-19 S1+S2 spike subunits, rivaroxaban did not modify citrate synthase activity with respect to the other experimental groups." (PMID 36438904, 2022). "We believe that better understanding of the CS, KKS, RAS and/or the Coagulation/Fibrinolysis systems, as well as how the interactions occur between them, and their consequences in the hemostasis, can contribute to a better understanding of the thrombotic state, observed in COVID-19." (PMID 35719336, 2022). "Consequently, in the context of COVID-19, C1-INH might mitigate uncontrolled CS activation and collateral lung damage, reduce capillary leakage and subsequent pulmonary edema, inhibit the generation of microthrombi via the KKS and CAS pathways, and preserve the regulatory role of endothelial cells." (PMID 39768234, 2024).
iron deficiency (5 papers, 2011 to 2026). "CS genes in trees are induced by iron deficiency and decrease after sufficient citrate accumulation or excessively high iron concentration." (PMID 41514946, 2026). "Western blot data for citrate synthase revealed that its expression was not changed with iron deficiency." (PMID 23171474, 2012). "In the present study the expression of citrate synthase, a non-iron containing enzyme of the citrate cycle, was unaffected by the iron deficiency in soleus muscle in both low-fat and high fat diet groups." (PMID 21589859, 2011). "Citrate synthase, a non-iron dependent mitochondrial enzyme, was not reduced with iron deficiency." (PMID 23171474, 2012). "Citrate synthase activity data also revealed no change with iron deficiency." (PMID 23171474, 2012). "Citrate synthase, a non-iron containing citrate cycle enzyme, and long chain acyl-CoA dehydrogenase (LCAD), used as a marker for the fatty acid oxidation pathway, were unaffected by the iron deficiency." (PMID 21589859, 2011).